SEC62 (SEC62 preprotein translocation factor)
Description:
Mediates post-translational transport of precursor polypeptides across endoplasmic reticulum (ER). Proposed to act as a targeting receptor for small presecretory proteins containing short and apolar signal peptides. Targets and properly positions newly synthesized presecretory proteins into the SEC61 channel-forming translocon complex, triggering channel opening for polypeptide translocation to the ER lumen.
Synonyms: TP-1; TLOC1; Dtrp1; HTP1
Tractability: Antibody: UniProt predicts a signal peptide or a membrane-spanning region. PROTAC: ubiquitination databases record sites on it; its protein half-life has been measured.
Gene: Protein-coding gene on chromosome 3 (169,966,635 to 169,998,373, forward strand). Ensembl gene ENSG00000008952.
Subcellular location: Endoplasmic reticulum membrane
Subcellular location (Human Protein Atlas): Endoplasmic reticulum; Intermediate filaments
Gene Ontology:
Molecular function: protein binding; protein transmembrane transporter activity; signaling receptor activity
Biological process: post-translational protein targeting to endoplasmic reticulum membrane; post-translational protein targeting to membrane, translocation; reticulophagy; cotranslational protein targeting to membrane; protein transport
Cellular component: endoplasmic reticulum membrane; membrane; endoplasmic reticulum; rough endoplasmic reticulum
Genetic constraint (gnomAD): Loss-of-function variants: 6 observed, 30.17 expected, observed/expected ratio (o/e) 0.2, 90% interval 0.11 to 0.39. The upper end of that interval is the gene's LOEUF score, 0.39, which puts it in group 1 of 6, group 1 being the genes least tolerant of losing a copy. Missense variants: 259 observed, 353 expected, observed/expected ratio (o/e) 0.73, 90% interval 0.66 to 0.81. Synonymous variants: 113 observed, 116.97 expected, observed/expected ratio (o/e) 0.97, 90% interval 0.83 to 1.13.
Homologues: Orthologues: chimpanzee SEC62 (100% identical), macaque SEC62 (99% identical), rabbit SEC62 (98% identical), dog SEC62 (98% identical), pig SEC62 (97% identical), guinea pig SEC62 (96% identical), mouse Sec62 (93% identical), rat Sec62 (93% identical), zebrafish sec62 (76% identical), Caenorhabditis elegans C18E9.2 (38% identical), Drosophila melanogaster Trp1 (38% identical).
Diseases named in the same sentence as SEC62 in open-access papers:
SEC62 is named in the same sentence as 40 diseases in open-access papers, as found by Europe PMC text mining. Sharing a sentence is not in itself a finding about the gene and the disease. The quoted sentences say what the papers report.
prostate carcinoma (15 papers, 2007 to 2023). A carcinoma that arises from epithelial cells of the prostate gland. "Subsequent studies identified SEC62 overexpression as a phenomenon associated with prostate cancer progression in patients and, in prostate cancer cells, as the reason for increased ER stress tolerance as well as increased migratory and invasive potential." (PMID 36262254, 2022). "Therefore, the Sec62 protein was suggested as potential diagnostic marker as well as therapeutic target in prostate cancer." (PMID 36262254, 2022). "In the year 2006, a first report associated the overexpression of the SEC62 gene, which is also termed TLOC1 and located at chromosome 3q26, with prostate cancer." (PMID 36262254, 2022). "A study showed that, by silencing Sec62, the migration and invasion of prostate cancer cells were significantly reduced with minimal effect on cell viability." (PMID 36359856, 2022). "For example, Sec62 has been found to confer resistance on thapsigargin analogs by ameliorating ER stress in prostate cancer." (PMID 36200182, 2022). "In 2006, a first study found SEC62 copy number gains in 7 of 13 prostate cancer samples as well as elevated Sec62 protein levels in three prostate cancer cell lines." (PMID 33925740, 2021). "Sec62 was previously characterised as a probable target gene in prostate cancer, lung cancer and thyroid carcinoma due to its high positive rate." (PMID 31822656, 2019). "Sec62 is highly elevated both at the mRNA and protein levels in prostate cancers and is positively correlated with decreased apoptosis in thapsigargin-treated cells, whereas, downregulation of Sec62 makes cells more responsive to this type of therapy." (PMID 30250843, 2018). "Over the past several years, the role of SEC62 as a potential oncogene has been shown in different tumors, including hepatocellular cancer, prostate cancer and HNSCCs." (PMID 28002801, 2017). "Previous studies demonstrated the amplification and overexpression of Sec62 in prostate cancer cell lines, and described SEC62 as a potential target gene in prostate cancer." (PMID 22682366, 2012). "Fluorescence in situ DNA hybridization (FISH) and quantitative real time PCR have been demonstrated to be valuable tools for target gene discovery within identified chromosomal regions of gain, e.g. the TLOC1/SEC62 gene at 3q26.2 in prostate cancer." (PMID 17712417, 2007). "Although several studies towards the role of Sec62 have mentioned it serves as an oncogene in malignant cancer, such as prostate cancer, non‐small‐cell lung cancer, thyroid cancer, cervical cancer cells, and human embryonic kidney cells, only a few have explored relevant underlying mechanisms." (PMID 36200182, 2022). "Analysis of various prostate cancer cell lines demonstrated that reduced Sec62 protein levels lead to larger Ca2+ leakage out of the ER and reduced cell viability while increased Sec62 expression correlated with protection against thapsigargin-induced apoptosis." (PMID 36277220, 2022). "Indeed, CaM inhibitors showed a functional Sec62 knockdown by blocking Ca2+ efflux from the ER lumen and inhibiting cancer cell migration in cervix and prostate cancer cells with inhibition of cancer cell proliferation at higher doses." (PMID 33925740, 2021). "Among the up-regulated genes, SEC62, which is reported to be overexpressed in lung cancer, prostate cancer, and thyroid cancer, is involved in endoplasmic reticulum stress tolerance and cell migration, and is identified as a prognostic marker for non-small cell lung cancer." (PMID 32697311, 2020). "Indeed, a siRNA-mediated SEC62 knock-down in vitro led to a highly effective inhibition of cancer cell migration in HNSCC, NSCLC, prostate cancer, and cervical cancer cells." (PMID 36045752, 2022).
prostate carcinoma (continued). "Correlations of IHC-detected SEC62 overexpression with poor clinical outcomes (i.e., reduced PFS and OS) have been reported for ovarian, non-small cell lung, head and neck, hepatocellular, and prostate cancers, with sample sizes ranging from 22 to 167 patients." (PMID 37298528, 2023). "Consistently, the migration potential of prostate cancer cells, NSCLC cells, thyroid cancer cells, and cervical cancer cells were markedly reduced by Sec62 knockdown, whereas the migration of cervical cancer cells and human embryonic kidney cells were promoted by Sec62 overexpression." (PMID 31822656, 2019).
cervical cancer (10 papers, 2006 to 2022). A primary or metastatic malignant neoplasm involving the cervix. "SEC62 overexpression has been associated with worse prognosis and high risk for lymphatic and distant metastases in head and neck cancer, cervical cancer, hepatocellular cancer, and lung cancer." (PMID 33915997, 2021). "In this study, we investigated copy number changes and the expression level of SEC62 encoded at 3q26.2 as a new potential 3q oncogene in dysplastic cervical lesions and analyzed its role in cervical cancer cell biology." (PMID 27553742, 2016). "In this study, we investigated the potential role of SEC62 in the carcinogenesis of cervical cancer." (PMID 27553742, 2016). "In functional analyses, we found that SEC62 overexpression promoted an invasive phenotype by stimulating the cervical cancer cells’ capability to migrate." (PMID 27553742, 2016). "SEC62 overexpression in tumor tissue compared with tumor-free tissue has been observed for lung, prostate, and cervical cancers at the protein and mRNA levels, and high SEC62 expression has been found to correlate with lymph node metastasis and poorer overall prognosis." (PMID 36685175, 2022). "Thus, we propose that SEC62 functions as a migration-stimulating oncogene in the carcinogenesis of cervical cancer and constitutes not only a potential marker for 3q26 amplification but also a potential target for anti-cancer treatment." (PMID 27553742, 2016). "Comparable to SEC62, SOX2 was amplified and overexpressed in different cancers, e.g., HNSCC, esophageal cancer, cervical cancer and lung cancer." (PMID 28002801, 2017). "We analyzed SEC62 and SOX2 expression in tissue specimens from 65 HNSCC patients and 29 patients with cervical cancer of unknown primary (CUP); a higher SEC62 and lower SOX2 expression was observed in the lymph node metastases from HNSCC patients compared with the respective primary tumor." (PMID 28002801, 2017).
head and neck squamous cell carcinoma (9 papers, 2017 to 2023). A squamous cell carcinoma that arises from any of the following anatomic sites: lip and oral cavity, nasal cavity, paranasal sinuses, pharynx, larynx, and salivary glands. "Similarly, an association of SEC62 overexpression with lymphatic metastasis was reported for head and neck squamous cell carcinoma as well as an association of SEC62 overexpression with distant metastasis in breast cancer." (PMID 33925740, 2021). "Various cancer types including head and neck squamous cell carcinomas (HNSCC) show a frequent amplification of chromosomal region 3q26 that encodes, among others, for the SEC62 gene." (PMID 36045752, 2022). "For non-small cell lung cancer, head and neck squamous cell carcinomas, and breast cancer, high SEC62 expression levels are a strong predictor of poor clinical outcome and correlate significantly with the presence of lymph node and/or distant metastases." (PMID 33915997, 2021).
hepatocellular carcinoma (9 papers, 2012 to 2022). A malignant tumor that arises from hepatocytes. "In hepatocellular cancer, high SEC62 expression is associated with a higher risk of recurrence after surgical treatment." (PMID 33915997, 2021). "Recent studies have reported that Sec62 is correlated with metastasis in breast cancer and promotes recurrence of hepatocellular carcinoma, suggesting that Sec62 is associated with cancer progression." (PMID 33858476, 2021). "Importantly, increased Sec62 protein levels are evident in post-surgical patients with HBV-related hepatocellular carcinoma recurrence." (PMID 30250843, 2018).
thyroid cancer (9 papers, 2013 to 2022). "High levels of SEC62 are associated with non-small cell lung cancer and thyroid cancer, and silencing SEC62 makes cells more sensitive to ER stress-induced death." (PMID 36408145, 2022). "Given the high positive rate of Sec62, it is regarded as a possible target gene for prostate, lung, and thyroid cancer." (PMID 36359856, 2022). "In non-small cell lung, prostate, and thyroid cancers, the increased expression of SEC62 can enhance the cellular tolerance of ER stress and can promote the invasion and metastasis ability of cancer cells." (PMID 35327508, 2022). "For thyroid cancer, increased Sec62 protein levels were observed in 40% and increased SEC62-mRNA levels in 60% of cases." (PMID 29263911, 2017). "Sec62 protein levels are significantly increased in different tumors, including prostate, lung and thyroid cancer." (PMID 24304694, 2013). "Thereby, 72% of all tumors showed detectable expression levels of SEC62 with the highest percentage of an increased expression compared with healthy tissue from the same origin in lung cancer (93–97%, depending on the subtype) and thyroid cancer (87–100%, depending on the subtype)." (PMID 29263911, 2017). "Therefore, SEC62 silencing seems to provide a potential approach for cancer treatment, especially lung and thyroid cancer, as such treatment could lead to reduced metastatic spread of tumor cells and higher sensitivity to chemotherapies working via the induction of ER stress." (PMID 24304694, 2013).
breast carcinoma (7 papers, 2021 to 2023). "In this study, we found that the 3q-encoded oncogene SEC62 is amplified in about 3% of all breast cancer cases and overexpressed in TNBC cells compared with physiological breast epithelial tissue." (PMID 37298528, 2023). "In a pilot study, we found that Sec62 protein expression was greater in breast cancer tissue samples than in tumor-free tissue samples from the same patients and that this high expression correlated with distant metastasis and poor overall survival (OS)." (PMID 37298528, 2023). "SKIL and SEC62 were identified as 3q26-resident tumor driver genes, as their overexpression contributes to the malignant transformation of lung, ovarian, and breast cancers." (PMID 37298528, 2023). "This study was conducted to investigate the role of SEC62, harbored at 3q26 and identified as a driver of breast cancer pathogenesis, in TNBC." (PMID 37298528, 2023). "In non-small cell lung cancer, breast cancer, and head and neck cancer, high SEC62 expression correlated with a significantly shorter overall survival, and the occurrence of lymph node and/or distant metastases." (PMID 33915997, 2021). "Given the identification of SEC62 as a potential driver of breast cancer development and its prognostic impact on other cancers, we further studied its role in the pathogenesis of breast cancer." (PMID 37298528, 2023). "However, our results are in line with the preliminary finding of Takacs and colleagues that SEC62 plays a prognostic role in breast cancer." (PMID 37298528, 2023). "Additionally, we found that the SEC62 expression level differed among breast cancer types and was highest in a small sample of patients with TNBC." (PMID 37298528, 2023). "In addition, the study was limited to TNBC, the breast cancer type with the greatest SEC62 expression; the role of SEC62 in other types of breast cancer needs to be evaluated further." (PMID 37298528, 2023). "Our analyses of TCGA data, which showed SEC62 alterations (mostly amplifications) in 32 tumor entities and shortened OS for patients with these alterations, support the potential role of SEC62 as a key tumor driver gene in various cancer entities, including breast cancer." (PMID 37298528, 2023). "With regard to a potential prognostic relevance of SEC62 expression, several studies reported a significant correlation of elevated Sec62 levels with poor patient prognosis in non-small cell lung cancer, breast cancer, liver cancer, and head and neck cancer." (PMID 33925740, 2021). "They evaluated the IHC Sec62 staining intensity in tissue samples from 53 patients using an IRS cut-off of 8 and determined that OS was worse in patients with SEC62 overexpression, independent of the breast cancer type." (PMID 37298528, 2023). "Regarding its role as an adverse prognostic biomarker, the results of our study are in line with previous reports that showed a correlation of high tumoral SEC62 expression with significantly shorter overall survival in HNSCC, melanoma, breast cancer, and NSCLC." (PMID 38201525, 2023).
gastric cancer (7 papers, 2020 to 2023). A primary or metastatic malignant neoplasm involving the stomach. "miR-4429 targeted and repressed METTL3 to inhibit m6A-mediated stabilization of SEC62, a component belonging to tetrameric Sec62/Sec63-subcomplex of Sec-complex, thus hindering proliferation and encouraging apoptosis in gastric cancer cells." (PMID 36614216, 2023). "SEC62 was expressed highly in gastric cancer compared to normal tissue, and SEC62 knockdown elevated cell proliferation." (PMID 36875073, 2023). "Increased Sec62 mRNA stability and expression subsequently lead to decreased apoptosis and increased gastric cancer cell survival." (PMID 35350378, 2022). "A correlation between higher SEC62 expression and advanced lymph node metastases has also been reported for NSCLC, melanoma, colorectal cancer, and gastric cancer." (PMID 38201525, 2023). "In gastric cancer, METTL3 promoted the mRNA stability of Sec62, which functions as a negative regulator of apoptosis, in an m6A/IGF2BP1 -dependent manner." (PMID 35350378, 2022). "Interestingly, miR-4429 inhibited the expression of METTL3, resulting in down-regulation of SEC62 expression, thereby preventing the progression of gastric cancer; LncRNA LINC00470 is significantly up-regulated in gastric cancer tissues and cell lines." (PMID 35070987, 2021). "Similarly, miR-4429, another potential therapeutic target in gastric cancer (GC), targets and downregulates METTL3 to inhibit m6A-induced stabilization of SEC62, which in turn inhibits cell proliferation and induces apoptosis in GC cells." (PMID 32443966, 2020).
lung carcinoma (7 papers, 2013 to 2021). "ML performed Ca2+ imaging, cell migration and real-time cell analysis experiments using the Sec62D308A variant, the human thyroid and lung cancer cell lines, compared Sec62 levels in different cell lines by western blot analysis, and participated in writing the manuscript." (PMID 24304694, 2013). "After analyzing the gene copy number and expression of SEC62 in tissue samples of NSCLC patients, we observed that lung cancer tissue shows a SEC62 amplification as well as SEC62 overexpression at both the mRNA and protein levels." (PMID 28002801, 2017). "N0) and cancer progression (G3 vs. G2) in SCC of the lung, the results indicate that Sec62 plays a crucial role in lung cancer biology and is both a promising new target for cancer therapy and a reliable marker of clinical outcomes." (PMID 24304694, 2013). "In lung cancer, the influence of Sec62 protein levels on patient survival was analyzed using the Kaplan-Meier method and log-rank test." (PMID 24304694, 2013). "The present study describes a new function of Sec62 in regulating the calmodulin-mediated sealing of the Sec61 Ca2+ leakage channel in the ER, which may explain how the up-regulation of SEC62 expression results in reduced survival among lung cancer patients." (PMID 24304694, 2013). "Because SEC62 silencing inhibits cancer cell migration and increases sensitivity to Ca2+-driven cellular stress, we investigated whether Sec62 represents not only a possible new target for anti-cancer therapies, but also a prognostic marker for lung cancer patients." (PMID 24304694, 2013). "Concurrently, functional analyses on lung cancer cell lines showed a marked reduction of the migratory potential of the cells after SEC62 knock-down and stimulation of HEK293 cell migration when the SEC62 gene was overexpressed." (PMID 28002801, 2017).
head and neck cancer (6 papers, 2017 to 2023). A primary or metastatic malignant neoplasm affecting the head and neck. "Together, SEC62 represents a promising and valid prognostic biomarker in this treatment setting of head and neck cancer." (PMID 38201525, 2023). "The role of SEC62 as a potential therapeutic target and its interaction with radiation-induced molecular alterations in head and neck cancer cells should further be investigated." (PMID 38201525, 2023). "In this study, we identified the expression of the SEC62 gene as a significant and independent predictor of patient outcome in a cohort of 127 head and neck cancer patients undergoing primary chemoradiation." (PMID 38201525, 2023). "Based on findings of functional assays and genomic database analyses, SEC62 has been identified as a potential driver of ovarian, lung, prostate, and head and neck cancers, and high SEC62 expression has been correlated with significantly shorter disease-free survival and overall survival." (PMID 37298528, 2023).
colorectal cancer (5 papers, 2021 to 2023). A primary or metastatic malignant neoplasm that affects the colon or rectum. "In colorectal cancer, Sec62 is activated by METTL3-mediated m6A modification, which enhances Wnt signaling by binding to β-catenin, thereby affecting the prognosis of colorectal cancer." (PMID 35774359, 2022).